NLRP3 (NLR family pyrin domain containing 3)
Diseases named in the same sentence as NLRP3 in open-access papers (continued):
Sharing a sentence is not in itself a finding about the gene and the disease.
age-related macular degeneration (38 papers, 2013 to 2025). Age-related loss of vision in the central portion of the retina (macula), secondary to retinal degeneration. "Studies of Nlrp3 knockout mice have exhibited a protective role for NLRP3 and associated IL-18 secretion in age-related macular degeneration." (PMID 34258050, 2021). "Recently, the NLRP3 inflammasome activation in the eyes has been known to be associated with the pathogenesis of age-related macular degeneration." (PMID 29854843, 2018). "The NLRP3 inflammasome is a central regulator of inflammation and its activation has been associated with several age-related diseases, such as Alzheimer’s disease, atherosclerosis, Parkinson’s disease, and age-related macular degeneration (AMD)." (PMID 34062977, 2021). "Contradictory data have been presented regarding the implication of the NACHT, LRR and PYD domains-containing protein 3 (NLRP3) inflammasome in age-related macular degeneration (AMD), the leading cause of vision loss in the Western world." (PMID 29323137, 2018). "Meanwhile, “NLRP3 inflammasome” and “model” from 2020, “age-related macular degeneration” from 2021, and “optical coherence tomography,” “identification,” and “gut microbiota” from 2022 have become the current research focuses in this field." (PMID 41048962, 2025). "The NLRP3 inflammasome has been implicated in various ocular diseases, including DES, uveitis, and age-related macular degeneration, due to its role in mediating inflammatory responses within the eye." (PMID 40299529, 2025). "Key areas of future exploration include the roles of the NLRP3 inflammasome and gut microbiota, the correlation between DR and age-related macular degeneration, and advancements in identification techniques and optical coherence tomography." (PMID 41048962, 2025). "A recent study of age-related macular degeneration (AMD) reported that IL-17A induces IL-1β secretion from retinal pigment epithelium (RPE) cells via NLRP3 inflammasome activation." (PMID 37109536, 2023). "Studies focusing on age-related macular degeneration have also reported NLRP3-inflammasomes-dependent cytokine induction of IL-1β and IL-18, both locally and systemically." (PMID 34071438, 2021). "It has been reported that BA suppresses inflammation by suppressing the activation of the NLRP3 inflammasome and it alleviates age-related macular degeneration via miR-223/NLRP3-regulated pyroptosis." (PMID 33111746, 2020). "The RPE dysfunction in age-related macular degeneration entails the NLRP3 inflammasome activation induced by Aβ-responsive oxidative stress." (PMID 33076507, 2020). "The central role of activation of NLRP3 inflammasome in retinal pigment epithelium cells as well as in models of age-related macular degeneration has also been reported." (PMID 29502235, 2018). "Thus, the controlled destruction of NLRP3 is a potential pathway to regulate the chronic inflammation, particularly in the development of age-related macular degeneration (AMD), as recently shown." (PMID 36139138, 2022). "Moreover, baicalin can alleviate pyroptosis in hepatocytes by inhibiting NLRP3-GSDMD signaling in vitro and reduces age-related macular degeneration through NLRP3-regulated pyroptosis." (PMID 34790063, 2021). "Age-related macular degeneration is regulated by the activation of NLRP3 inflammasome signaling." (PMID 32984347, 2020). "In age-related macular degeneration (AMD), several examples of activators of the NLRP3 inflammasome have been identified, e.g., drusen and lipofuscin components, cathepsin B leaking from damaged lysosomes, and oxidative stress." (PMID 34062977, 2021). "The membrane attack complex (MAC) is a key player in the pathogenesis of age-related macular degeneration (AMD) and is a putative activator of the NLRP3 inflammasome." (PMID 26104676, 2015).
age-related macular degeneration (continued). "In studies involving age-related macular degeneration (AMD), DR, and other retinopathies, researchers found that the NLRP3 inflammasome activation was the key factor leading to the proinflammatory effect, but the specific mechanism remains unknown." (PMID 33093455, 2020). "Accumulation of the long noncoding Alu element RNA activates the NLRP3 inflammasome and leads to retinal pigment epithelium (RPE) cell death, a key event in the pathogenesis of geographic atrophy during late-stage age-related macular degeneration." (PMID 32855848, 2020). "Activation of the inflammasome is involved in the progression of retinal degenerative diseases, in particular, in the pathogenesis of Age-Related Macular Degeneration (AMD), with NLRP3 activation the focus of many investigations." (PMID 32041990, 2020). "In patients with age-related macular degeneration (AMD), increased mRNA levels of NLRP3, IL-1β, and pro-IL-18 in lesions of the retinal pigment epithelium and photoreceptors were detected." (PMID 28273882, 2017). "Furthermore, aberrant expression of Alu RNAs within retinal pigmented epithelium induces TLR-independent activation of the NLRP3 inflammasome, leading to geographic atrophy, a form of age-related macular degeneration (AMD)." (PMID 26584434, 2015). "NLRP3 inflammasome activation and complement-mediated inflammation have been implicated in promoting choroidal neovascularization (CNV) in age-related macular degeneration (AMD), but central questions regarding their contributions to AMD pathogenesis remain unanswered." (PMID 33305736, 2020). "Moreover, activation of the NLRP3 inflammasome might result from the instability of lysosomes in retinal pigment epithelial cells, which can aggravate conditions like age-related macular degeneration (AMD)." (PMID 39286668, 2024). "Blocking pyroptosis by targeting the assembly of NLRP3 inflammasomes and GSDMD emerges as a potential therapeutic approach for addressing neuroinflammation and neurodegeneration-related conditions, including age-related macular degeneration (AMD) and Alzheimer’s disease." (PMID 39065688, 2024). "The NLRP3 inflammasome activation is induced by Aβ via reactive oxygen species (ROS)-dependent oxidative stress, which may be responsible for RPE dysfunction in age-related macular degeneration." (PMID 33076507, 2020).
pancreatic cancer (38 papers, 2015 to 2025). "NLRP3 can affect immune microenvironment of pancreatic cancer by regulating polarization state of tumor-associated macrophages." (PMID 40535567, 2025). "Another study demonstrated that LPS-induced inflammation can activate NLRP3 in the presence of ATP, while NLRP3 would then increase the propagation of pancreatic cancer cells by increasing the activity of caspase-1, causing production of IL-1β." (PMID 38182564, 2024). "For instance, NLRP3 has been associated with increased frequency of the rs35829419-NLRP3 polymorphism in patients with pancreatic cancer, suggesting a potential genetic association with the disease." (PMID 39769450, 2024). "Inflammasomes have been implicated in many types of cancer, including in pancreatic cancer where the NLRP3 inflammasome modulates inflammation and single nucleotide polymorphisms (SNPs) in the NLRP3 gene are common in pancreatic cancer patients." (PMID 37342194, 2023). "Our study demonstrated that the prevalence of rs35829419 (Q705K, NLRP3) polymorphism is higher in subjects with pancreatic cancer and that of rs17699678 (F359L, NLRP2) polymorphism is higher in the group of chronic pancreatitis." (PMID 26253076, 2015). "In conclusion, the study revealed that the NLRP2 polymorphism was associated with chronic pancreatitis, whereas the NLRP3 polymorphism was comorbid with pancreatic cancer." (PMID 26253076, 2015). "Therefore, we aimed to explore the prognostic role and diverse interactions of NLRP3 inflammasome proteins and associated cytokines in pancreatic neoplasms." (PMID 39969214, 2025). "Moreover, the NLRP3 inflammasome has been implicated in promoting pancreatic islet damage, indicating its possible involvement in the pathophysiology of pancreatic cancer." (PMID 39769450, 2024). "Additionally, upregulation of NLRP3 signaling has been linked to promoting platelet activation and aggregation, leading to tumor growth and metastasis in a mouse model of pancreatic cancer." (PMID 39769450, 2024). "Therefore, the aim of this study was to evaluate periodontal status in reference to a single-nucleotide polymorphism (SNP) of NLRP2: F359L (rs17699678 C>T) and NLRP3: Q705K (rs35829419 C>A) in patients with pancreatic cancer and chronic pancreatitis as well as in the control group." (PMID 26253076, 2015). "Chronic, NLRP3 inflammasome‐driven inflammation is potentially significant in developing pancreatic cancer." (PMID 39969214, 2025). "Its ability to inhibit IL-18/NLRP3-regulated NICD suggests potential for microvascular-targeted pancreatic cancer treatment strategies." (PMID 40422787, 2025). "In pancreatic cancer, NLRP3 and its mediated inflammatory response are considered to significantly impact progression and occurrence of tumor." (PMID 40535567, 2025). "In contrast, in gastric, hepatocellular, and pancreatic cancers, research has confirmed that the stimulation of NLRP3 inflammasomes promotes the invasion and metastasis of cancer cells." (PMID 38182564, 2024). "For example, downregulation of NLRP3 has been shown to inhibit the proliferation and migration of pancreatic cancer cells, suggesting a potential tumor-suppressive role." (PMID 39769450, 2024). "In contrast, NLRP3 signaling in TAMs in pancreatic cancer drives macrophage-induced immunosuppression, thereby inhibiting CD8+ T-cell activation." (PMID 38062129, 2024). "The NLRP3 inflammasome has been shown to promote immune evasion in pancreatic cancer, specifically by differentiating T cells into pro-tumor populations (Th2, Th17, and T regs) and preventing the activation of tumor-killing CD8+ T cells." (PMID 37342194, 2023). "We show that NLRP3 is highly expressed in pancreatic cancer tissue when compared with the normal pancreas." (PMID 37772994, 2023). "According to a previous study, LPS-induced inflammation in the presence of ATP activates NLRP3, which enhances pancreatic cancer cell proliferation by boosting caspase-1 activity, resulting in total IL-1β production." (PMID 35677632, 2022).
pancreatic cancer (continued). "NLRP3 in platelets is upregulated with increased caspase-1 activity in pancreatic cancer, as demonstrated in a mouse model." (PMID 33923537, 2021). "A recent study reported that the platelet NLRP3 inflammasome was upregulated in a murine model of pancreatic cancer and promoted platelet aggregation and tumor growth." (PMID 33728029, 2021). "In a murine model of pancreatic cancer, the platelet NLRP3 inflammasome is upregulated and promotes platelet aggregation and tumor formation." (PMID 33923537, 2021). "To furtherly analyze the role of the NLRP3 inflammasome in pancreatic cancer progression, we selected a novel specific NLRP3 inflammasome inhibitor, MNS." (PMID 32974137, 2020). "Based on the results of the present study, we confirmed that MNS inhibits pancreatic cancer cell growth through suppressing NLRP3 inflammasome." (PMID 32974137, 2020). "The impact of NLRP3 inhibition on migration, invasiveness, and proliferation of pancreatic cancer cells was analyzed through wound healing assay, Transwell assay, and Cell Counting Kit-8 (CCK-8) assay, respectively." (PMID 32974137, 2020). "Western blot analysis showed significant expression of NLRP3 inflammasome in human pancreatic cancer lines SW1990 and PANC-1, and MNS did significantly inhibit the expression of NLRP3 inflammasome in cell lines." (PMID 32974137, 2020). "Western blot was used to evaluate the NLRP3 inflammasome expression in pancreatic cancer cell lines SW1990 and PANC-1." (PMID 32974137, 2020). "For example, lncXLOC_000647 down‐regulates the expression of its neighbouring gene NLRP3 to suppress the progression of pancreatic cancer." (PMID 32770626, 2020). "The combining antitumor effect in vivo of CIK and NLRP3 inhibition was evaluated in a subcutaneous human pancreatic cancer BALB/c nude mouse model." (PMID 32974137, 2020). "XLOC_000647 served as a tumor suppressor, impairing cell proliferation, invasion, and epithelial-mesenchymal transition abilities through NLRP3 inhibition in pancreatic cancer." (PMID 30250401, 2018). "Curcumin effectively attenuated the inflammatory microenvironment of pancreatic cancer by modulating a complex signaling network that downregulates NLRP3, CASP1 and CSF2 while simultaneously regulating expression of key pro-inflammatory factors within interleukin family." (PMID 40535567, 2025). "Given that NLRP3 inflammasome activation and IL-18 production are critical in pancreatic cancer progression and considering IL-18’s role as a CXCR1/2 ligand promoting tumorigenesis and angiogenesis, 8 represents a promising marine-derived therapeutic candidate." (PMID 40422787, 2025). "However, additional studies are still needed to clarify the role of NLRP3-mediated immune and inflammatory responses in pancreatic cancer progression and therapy." (PMID 39769450, 2024). "In related studies, investigators followed several pancreatic cancer patients and assessed their NLRP3 expression using immunohistochemical techniques, in addition to assessing the relationship between survival and NLRP3 expression in these patients by using Kaplan–Meier curves." (PMID 38182564, 2024). "There is also evidence for the ability of NLRP3 signaling to contribute to the establishment of an immunosuppressive microenvironment in pancreatic cancer by promoting T cells to undergo tolerogenic differentiation and through the IL-10-mediated suppression of adaptive immunity." (PMID 37885032, 2023). "It is known that NLRP3 signaling drives resistance to anti-PD-1 immunotherapy and is responsible for adaptive immune suppression through promoting the production of IL-1β in pancreatic carcinoma." (PMID 36900234, 2023). "In the pancreas, NLRP3 activation was found to be necessary for the development of experimental acute pancreatitis, pancreatic fibrosis, obesity-induced insulin resistance, and to be a critical inflammatory mechanism in pancreatic cancer." (PMID 36619871, 2022).
pancreatic cancer (continued). "The evidence presented in this study shows that NLRP3-regulated IL-18-induced eosinophilic inflammation may be involved in promoting the pathogenesis of pancreatic neoplasm via the indicated pathways and promotes characteristics similar to human cancer." (PMID 34183442, 2021). "In the present study, we demonstrate that MNS can induce suppression of proliferation, migration, and invasion of human pancreatic cancer cells through inhibiting NLRP3 inflammasome in vitro and in vivo, combining with CIK cells to exert a more aggressive antitumor effect." (PMID 32974137, 2020). "Blockade of NLRP3 may be a promising immunotherapy for pancreatic carcinoma, which drives macrophage-induced adaptive immune suppression." (PMID 31312615, 2019). "In addition, some studies have suggested the protective role of NLRP3 in pancreatic cancer." (PMID 39769450, 2024). "In addition, several studies have noted the influence of NLRP3 in pancreatic cancer." (PMID 39769450, 2024). "In short, NLRP3 could promote the tumor growth, progression and cell invasion in pancreatic cancer." (PMID 36619871, 2022). "Moreover, NLRP3 inhibition could significantly decrease the migration, invasiveness, and proliferation of pancreatic cancer cells." (PMID 32974137, 2020). "However, Whether NLRP3 inflammasome contributes to proliferation and metastasis of pancreatic cancer is still unknown." (PMID 32974137, 2020). "In summary, RP-6306 not only facilitates GSDMD cleavage but also robustly activates a network of upstream signaling pathways including NLRP3, AIM2, and Caspase-1 in pancreatic cancer cells." (PMID 40664640, 2025). "An additional NLRP3-mediated feature in the PDA onset is platelet aggregation, which further enhances pancreatic cancer progression and lymph node invasion." (PMID 37891577, 2023). "Excitingly, we found a recent report that more completely elaborates the role of NLRP3, CASP1, and IL-β in pancreatic cancer." (PMID 35677632, 2022). "RNA sequencing analysis of the pancreatic tumors demonstrates the role of the combination of STING/NLRP3 agonist and chemotherapy, but not either treatment modality alone, in upregulating the T cell activation signaling." (PMID 39871312, 2025). "TMEM176B inhibits NLRP3 inflammasome activation to regulate adaptive and innate antitumor responses, suggesting that TMEM176 may be a potential immunotherapy target for pancreatic cancer." (PMID 37265785, 2023).